NOTCH3 (notch receptor 3)
Diseases named in the same sentence as NOTCH3 in open-access papers (continued):
Sharing a sentence is not in itself a finding about the gene and the disease.
cancer (continued). "In addition to the Wnt/β-catenin signaling pathway, we demonstrated that KLF10 contributed to the cancer stemness phenotype by transcriptionally regulating Notch-3 and Notch-4 and competing with E74-like ETS transcription factor 3 (ELF3) for promoter binding." (PMID 37958386, 2023). "Remarkably, even under nanomolar (nM) concentrations of the miR-206, Au-PEG-miRNA NPs triggered cancer cell death by hindering the expression of a well-known target of miR-206, neurogenic locus notch receptor 3 (NOTCH3, responsible for cell proliferation and tumorigenesis)." (PMID 37576994, 2023). "We analyzed Notch3 expression in myofibroblast and in cancer cells." (PMID 36854682, 2023). "In contrast, expression of Notch3 by cancer cells had an impact and was of good prognosis." (PMID 36854682, 2023). "In addition to NOTCH1, NOTCH3 signaling was also considered to be important in several types of cancers." (PMID 35900231, 2022). "NOTCH3 signaling is a well-known pathway contributing to cancer development." (PMID 36386788, 2022). "Targeting NOTCH3 is proposed as new promising therapy in other cancers as well." (PMID 35073251, 2022). "The aberrant high expression of Notch3 is common in human cancer tissues, as shown in several studies, as well as the Cancer Genome Atlas (TCGA) and Oncomine database." (PMID 34195229, 2021). "In addition, the concomitant administration of DAPT or the selective inhibition of Notch3 by siRNA and paclitaxel showed a synergic effect on promoting cancer cell death through activation of the intrinsic apoptotic pathway." (PMID 34680255, 2021). "On the other hand, Notch3 signaling mediated spontaneous lung metastasis in estrogen receptor alpha-positive (ERα+) breast tumor xenografts by sustaining the self-renewal and high invasive properties of a population of metastatic cancer cells." (PMID 34680255, 2021). "A major role of Notch3 is maintaining the stemness of cancer stem cells (CSCs)." (PMID 34195229, 2021). "The clinical significance of Notch3 in different types of cancer." (PMID 34195229, 2021). "Additionally, we observed that METTL3 is involved in the modulation of Notch signaling pathway (including METTL3 DLL3, HES1, and NOTCH3 genes) (q-value < 0.05), which plays an important role in tumorigenesis and cancer development." (PMID 34589481, 2021). "Both NOTCH3 and PKCλ are highly expressed in basal-like cancers at all stages." (PMID 32658903, 2020). "Given the observation that NOTCH3 has prognostic value in GC, the RNA expression data in The Cancer Genome Atlas (TCGA) database were also used to analyze the prognostic potential of NOTCH3 in other gastrointestinal (GI) cancers, including LIHC, ESCA, COAD, and PAAD." (PMID 33479597, 2020). "Induction of Notch3 by CAFs led to an increase in proliferation of cancer stem cells." (PMID 32028262, 2020). "Moreover, Notch3 triggered by stromal cell-derived exosomes activated antiviral signaling depending on STAT1 in cancer cells." (PMID 32028262, 2020). "Receptor Notch-3 is a notorious molecule for cancer propagation." (PMID 33255653, 2020). "The effects of miR-206 on Notch3 signalling in cancer cells translates to pulmonary vascular cells." (PMID 31868216, 2019). "Notch3 is activated when it binds to its ligand Jagged1, and COMP can bind both molecules (Notch3 and Jagged1) and increase their interaction, leading to a higher activation of the Notch pathway and cross-talking with other important cancer related molecular pathways, such as AKT and β-catenin." (PMID 31737569, 2019). "In addition, siRNA‐mediated knockdown of NOTCH3 in HuH7 cells resulted in a decrease in spheroid formation, suggesting that NOTCH3 is an important mediator of CD44‐mediated maintenance of cancer stemness in HuH7 cells." (PMID 30636370, 2019). "Finally, we have proved that this mechanism can be extended to other human cancer cells, thus suggesting that Notch3 inhibition holds a promise as a general strategy to improve brivanib effects." (PMID 30765875, 2019).
cancer (continued). "NOTCH3 was previously found to be overexpressed in several types of cancers." (PMID 31064135, 2019). "Additionally, Notch3 up-regulation and overactivation have been demonstrated in various cancers, particularly ovarian and non-small cell lung cancers." (PMID 31868216, 2019). "Immunofluorescence analysis showed a higher percentage of vMCF-7Raf-1 1GX-M cells expressing NOTCH3 than their matching vMCF-7Raf-1 1GX cells, suggesting that NOTCH3-expressing cancer cells exhibited a higher capacity to promote seeding and growth to distant organs." (PMID 30180881, 2018). "Owing to the limited translatability of established cancer cells, and to corroborate the central role of NOTCH3 in driving a metastatic phenotype in clinically relevant models, we established unique TNBC cells (TNBC-M25) isolated from a patient-derived brain metastasis xenograft model." (PMID 30180881, 2018). "Next, we aimed to establish whether pharmacologic targeting of NOTCH signaling inhibits metastatic seeding and growth of cancer cells overexpressing NOTCH3." (PMID 30180881, 2018). "Because of this, Notch3 has become a target for novel cancer therapies." (PMID 28922540, 2017). "Furthermore, co-culturing LLC1 cells with HUVEC was sufficient to induce an upregulation of Notch3 in the endothelial cells, showing that the epithelial cancer cells are sufficient to induce Notch3 expression in endothelial cells." (PMID 28719575, 2017). "Interestingly, we now have data showing that the Notch signaling pathway, Notch3 in particular, plays a key role in cancer stem cell (CSC) maintenance and paclitaxel(PTX)-resistance." (PMID 29069826, 2017). "Interestingly, a significant positive correlation between Notch-1 and Syndecan-1 mRNA levels (r = 0.793, P = 0.001) and between Notch-3 and Syndecan-1 mRNA levels (r = 0.819, P = 0.001) did exist in carcinoma tissues of IBC." (PMID 28270211, 2017). "In this study, we demonstrated a negative regulation of Notch3 by NAC in cancer cells." (PMID 27102435, 2016). "Additional cancer cells were employed to explore whether the inhibitory effect of NAC on Notch3-meditated malignancy is cell-specific or a general pathway." (PMID 27102435, 2016). "Double immunofluorescent staining of NOTCH3 and keratin in this coculture model showed that bundles of NOTCH3-positive NHDFs surrounded keratin-positive HO1-N-1 cancer nests, which resembled the distribution of NOTCH3-positive fibroblasts around the cancer nests in the human OSCC samples." (PMID 27124156, 2016). "To investigate whether NOTCH3 induction in fibroblasts is a unique property of OSCCs, we cocultured NHDFs with cell lines derived from cancers of various organs including uterine cervix, lung, breast, stomach, colon, and pancreas." (PMID 27124156, 2016). "In addition, three potential Notch3-dependent cancer cell lines ZR-75-1, OVCAR-3 and MCF-7 were used to evaluate the effects of NAC on Notch3 protein levels and cell proliferation." (PMID 27102435, 2016). "Furthermore, through the soft agar assay, they demonstrated that Notch3 silencing affects osteoblast-induced anchorage-independent growth in cancer cells." (PMID 27571063, 2016). "Therefore, targeting the Notch3 pathway represents a promising therapeutic strategy for cancers with dysregulated Notch3 signaling." (PMID 25356737, 2014). "NOTCH3 expression was generally unchanged in cancer tissues." (PMID 25167871, 2014). "This article is the first study, to our knowledge, that delineates the Notch3 interacting network, and demonstrates that one of the Notch3 interacting proteins, WWP2, an E3 ubiquitin-protein ligase, plays a major role in negative regulation of Notch3 signaling in cancer cells." (PMID 25356737, 2014).
cancer (continued). "In addition, Notch 3 overexpression increases the proportion of cancer stem cell-like cells (CSCs) and resistance to platinum-based therapy." (PMID 25356737, 2014). "NOTCH3 is frequently deregulated in many malignancies and its role in cancer is now firmly confirmed, hence may play major role in gliomagenesis." (PMID 24143218, 2013). "Therefore, WWTR1-AS1 may upregulate Notch3 through miR-136 to increase cancer cell stemness in CSCC." (PMID 38331752, 2024). "Moreover, it was demonstrated that the expression of EMT indicators in the co-culture group was upregulated at the mRNA and protein levels, and the cancer stemness index including Nanog, Notch-3, and Oct-4 were also observed to be upregulated at mRNA and protein level." (PMID 37330523, 2023). "COMP increases the interaction between Notch3 and its ligand Jagged1, causing higher activation of Jagged1-Notch3 signaling and cross-reactivity with other important cancer-related pathways, such as AKT and β-catenin, resulting in the generation of a large number of cancer stem cells." (PMID 36012514, 2022). "Finally, we summarize known Notch3-targeting strategies/methods for cancer therapy." (PMID 34195229, 2021). "Therefore, complementary to the lower infiltration of CD8+ T cells, these checkpoint inhibitors form a counter-regulatory mechanism in cancer cells putatively driven by the high expression of NOTCH3, indicating a new mechanism of NOTCH signaling for facilitating immune escape." (PMID 33479597, 2020). "In addition, NOTCH3 also has been reported to play an oncogene part in other cancers." (PMID 32343052, 2020). "This ‘initial survival’ of cancer cells from targeted therapy against driver oncogenes has recently been highlighted in epidermal growth factor receptor (EGFR)-mutated tumors, and the Notch-3/β-catenin pathway or AXL has been shown to play a key role in this survival." (PMID 31900393, 2020). "In addition, NOTCH3 was shown to be critical for the cancer stemness of HuH7 cells." (PMID 30636370, 2019). "Indeed, IL-6 requires Notch3 activity to promote cancer cell invasion and self-renewal." (PMID 30154786, 2018). "Also, HLA-A, MED1, NOTCH2 and NOTCH3 are related with cancer prognosis." (PMID 30545040, 2018). "Notch3 signaling plays an important role in the proliferation of ErbB2-negative breast tumor cells and its targeted suppression may be a promising strategy for this cancer treatment." (PMID 28036048, 2016). "Thus, cell-to-cell contact between cancer cells and CAFs may lead to the production of paracrine factors that can stimulate NOTCH3 expression in CAFs." (PMID 27124156, 2016). "LUAD exhibited a particularly high number of 7 mutated genes with significant co-occurrence with CNAs compared to other cancer types – including EGFR, GATA2, GBA, GLI3, KAT6A, KRAS and NOTCH3." (PMID 41415395, 2025). "The levels of NOTCH3 are higher in NSCLC tumors, compared to the adjacent tissues, and correlate with the clinical stage of cancer and metastasis." (PMID 40155749, 2025). "NOTCH3 and NOTCH4 regulate genes involved in BCAA catabolism, thereby affecting the TME and cancer cell metabolism." (PMID 39286249, 2024). "In our study, NOTCH3 was one of the top up-regulated genes in the NOTCH pathway, commonly aberrantly expressed in human cancers." (PMID 39061234, 2024).
cancer (continued). "The Notch3 pathway is heavily involved in CSC development, proliferation, and chemoresistance of different drugs for multiple cancers and is often activated through cell-cell contact." (PMID 39802952, 2024). "Investigating the proteins driving cluster 1, we found lower levels of circulating proteins regulating DNA repair/integrity (RBBP8, RAD21) and cell fate/replication (NOTCH3, TJP3, HNRNPA2), which play a role in cancer development." (PMID 35033985, 2022). "Although the use of immunotherapy in PDAC remains an unmet challenge, recent insights indicated a potentially significant role of the PD-L1/Notch3 axis in SCP, opening new horizons for immunotherapy in this cancer subtype." (PMID 35163206, 2022). "Based on our data, activated forms of Notch1, Notch2, Notch3, and Notch4 (N1ICD, N2ICD, N3ICD, and N4ICD) in stomach-cancer cells were all upregulated, especially N1ICD and N2ICD, after the co-culture of cancer cells and macrophages." (PMID 35382168, 2022). "Our results indicated NOTCH1, NOTCH3, FLCN, SOD1, SOD2, NF1, and TLR4 as upregulated proteins in different cancer types highlighting their role in cancer progression." (PMID 35001007, 2022). "TCGA database was used to analyze the expression of NOTCH3 and SMARCA4 in the CRC tissues and the adjacent normal tissues, and the results revealed that both of them showed higher expression in cancer tissues when compared to the adjacent tissues." (PMID 35900231, 2022). "Mechanistically, Notch3 signaling activates LSD1, a histone-modifying enzyme that promotes cancer stemness, by inducing its deacetylation by activating the class-III histone deacetylase (HDAC) SIRT1." (PMID 34195229, 2021). "However, in SCC, another necessary step in TGFβ-Notch1 induction of EMT is ZEB1-dependent inhibition of Notch3, suggesting that Notch1 and Notch3 may have different cancer-dependent roles in EMT induction and highlighting that the use of pan-Notch inhibitors may not be universally useful." (PMID 34680255, 2021). "The miR-491-5p/miR-875-5p-NOTCH3-PHLDB2 regulatory cascade is involved in gastric carcinogenesis and promotes cancer progression." (PMID 33452458, 2021). "WNT3A regulates cancer cell stemness and increases metastatic potential via CTNNB1 signaling pathway and upregulation of Notch3 31,32." (PMID 34093821, 2021). "We first evaluated the expression correlation of NOTCH3 with epithelial–mesenchymal transition (EMT) and cancer stemness markers." (PMID 33452458, 2021). "NOTCH3 regulates CSC activities including cell proliferation, anoikis-resistance, colony-formation, drug-resistance, and SP in various cancer cells, including EOC." (PMID 33316986, 2020). "In the CHRNB4-high subgroup, CHRNB4 was co-expressed with numerous genes, such as ADCY9, NOTCH3, ARNT, NCOA1, and NCOA3, which correlated with multiple cancer-related processes, but only one gene, FLT4, was co-expressed in the CHRNB4-low subgroup." (PMID 32455963, 2020). "This analysis found that AC009283.1 knockdown altered the expression of NOTCH3, TNFa and FOSB, genes that have been previously suggested to be drivers for proliferation and cell cycle in cancer." (PMID 32753692, 2020). "Clinical data indeed show that NOTCH3 contributes to cancer malignancy selectively in NRF2-activated NSCLCs, strongly suggesting pathological significance of the NRF2-NOTCH3 axis." (PMID 33219226, 2020). "In this review, we draw a picture on the current knowledge about the role of Notch3 in ovarian CSC behavior regulation, in order to suggest potential Notch3 inhibition-based cancer treatments aimed at improving the prognosis of OC patients." (PMID 30723507, 2019).
cancer (continued). "Although the detailed molecular mechanism remains to be clarified, our data suggest that NOTCH3 is an important mediator for the induction and maintenance of CSCs by CD44s in HCC as in other cancers." (PMID 30636370, 2019). "The therapeutic potential of Notch3 inhibition combined with brivanib treatment was also demonstrated in a rat model of HCC and in cell lines derived from different human cancers." (PMID 30765875, 2019). "Reports indicate that NOTCH-3, JAG-1, and DLL-4 are among the most altered notch signaling genes in cancer." (PMID 26762567, 2016). "Overall, our results provide mechanistic insight into a novel suppression of Notch3 and its malignant signaling by NAC in cancer cells, suggesting a promising application of NAC targeting Notch3-mediated carcinogenesis." (PMID 27102435, 2016). "By contrast, the inhibition of Notch3 by γ-secretase inhibitor (GSI) induces apoptosis and suppresses the proliferation of cancer cells through the downregulation of the pro-survival proteins, pBcl-2 and pBcl-xL, and not Bax in NSCLC." (PMID 24919811, 2014). "Similarly, activated NOTCH2, NOTCH3, NOTCH4 signalling are correlated with more aggressive cancer and poor prognosis." (PMID 38926351, 2024). "There was a weak negative correlation between NOTCH3 expression and the overall survival (ρ = −0.103, p < 0.001) and cancer-specific mortality (ρ = −0.068, p < 0.05)." (PMID 35073251, 2022). "In SCLC, it can be observed that cancer gene alterations appear to be more frequent in women, the most consistent differences being observed in PTRD, CREBBP, GRM3, ATRX, NOTCH3, and PDE4DIP, while ATM appears to be altered in 5.26% of men, and no alterations were depicted in women." (PMID 35330454, 2022). "Consistently, depletion of NOTCH3, NUAK1, or PDPK1 decreased cancer cell migration." (PMID 36072578, 2022). "NOTCH3 increases the expression of COL4A2, which makes cancer cells more resistant to anoikis." (PMID 35159353, 2022). "Similarly, the network figures for the remaining networks show similar positioning for many important cancer genes: NOTCH1 in liver, NOTCH3 and EGFR in lung are some other examples." (PMID 34115745, 2021). "The shNOTCH3 groups formed smaller and less number of nodules than the negative control group, suggesting NOTCH3 knockdown inhibits the peritoneal metastatic abilities of the cancer cells." (PMID 33452458, 2021). "Pathways derived from NOTCH3, PARD3, CACNA1A, MAX, RAD50, FUS and LMO2 were cancer-related." (PMID 34540367, 2021). "Both migration and invasion of A549 and PC9 cells were significantly promoted by TANs, while after knocking down Notch3, the migration and invasion of the cancer cells were not affected by TANs." (PMID 35118116, 2021). "Notch 3 acts as a critical regulator of pathological blood vessel formation and its abnormal activation spurs neoangiogenesis in different cancers as stated by several research groups but no data are available concerning NHLs." (PMID 33374160, 2020). "Moreover, a strong correlation between Notch3 and CCNG1 expression levels supports a role of both Notch3 and CCNG1 in cancer progression." (PMID 30565428, 2019). "Given that APL13 can stimulate JAG1/Notch3 signaling in ischemic hearts, in this study we investigated whether the treatment with APL13 activates JAG1/Notch3 to promote cancer proliferation in CRC." (PMID 29254197, 2017). "This further supports the view that Notch3 induces endothelial cell death independently of Notch canonical signalling pathway, and that the expression of Jag-1 by cancer cells can cell non-autonomously rescue endothelial cell death." (PMID 28719575, 2017). "This feed-forward circuit with DLL4, Notch3, MSI-1, NUMB and Notch1 may be relevant for the regulation of Notch during cancer formation." (PMID 29104587, 2017). "The expression of NOTCH-3 and JAG-1 is highly correlated and found to be upregulated in cancer." (PMID 26762567, 2016).